RN7SKP225 (RN7SK pseudogene 225)
Gene: Miscellaneous RNA gene on chromosome 9 (99,284,022 to 99,284,373, forward strand). Ensembl gene ENSG00000222337.
Homologues: Orthologues: chimpanzee 7SK (99% identical), mouse Gm56172 (19% identical). Paralogues in human: RN7SKP124 (68% identical), RN7SKP133 (67% identical), RN7SKP217 (67% identical), RN7SKP162 (66% identical), RN7SKP294 (66% identical), RN7SKP230 (66% identical), RN7SKP79 (66% identical), RN7SKP203 (65% identical), RN7SKP249 (65% identical), RN7SKP250 (65% identical), RN7SKP77 (65% identical), RN7SKP180 (65% identical), and 283 more.